MIR4771-1 (microRNA 4771-1)
Synonyms: hsa-mir-4771-1
Gene: MicroRNA gene on chromosome 2 (87,194,786 to 87,194,859, forward strand). Ensembl gene ENSG00000264793.
Homologues: Paralogues in human: MIR4771-2 (100% identical).